AFP (alpha fetoprotein)
Diseases named in the same sentence as AFP in open-access papers (continued):
Sharing a sentence is not in itself a finding about the gene and the disease.
tumor (continued). "High AFP tumours were particularly associated with the proliferation and the S2 classes, with a consistent enrichment of gene signatures defining progenitor features and overexpression of the known epidriver IGF211 when compared with AFP-low tumours." (PMID 31285588, 2019). "AFP is the most commonly used tumor marker of HCC; however, its sensitivity is only 60%." (PMID 31281549, 2019). "Similarly, for DFS of HCC patients, univariate analyses revealed that CKS2 expression, tumor size, AFP, portal vein invasion, HBsAg, TNM stage, and metastasis were potential factors." (PMID 31781310, 2019). "A number of therapeutic approaches have been described to improve preexisting antitumor immunity, including recombinant plasmid DNA, chimeric virus-like particles, viral or bacterial vectors expressing AFP proteins, and adoptive transfer of tumor-specific T cells." (PMID 29805966, 2018). "Finally, the results of the combined OR showed that LDH was significantly correlated with gender, Child-Pugh grade, AFP, vascular invasion, and tumor size." (PMID 30687735, 2018). "High GSTP1 was correlated with low serum AFP (P = 0.003) and small tumor size (P = 0.013)." (PMID 29507666, 2018). "Univariate and multivariate analyses demonstrated that preoperative serum AFP, vascular invasion, within or downstaged to Milan criteria, tumor diameter, tumor nodules, and tumor differentiation were found to be independent factors that influenced the incidence of PM." (PMID 29416782, 2018). "Tumor marker tests detected significantly high levels of AFP in serum." (PMID 30314476, 2018). "Moreover, comparison between HCC patients with tumor size >3 cm revealed a significantly higher values versus those with tumor size ≤3 cm as regards AFP and lamin B1 (Z=3.1, p<0.01 and Z=4.6, p<0.001), respectively." (PMID 30467522, 2018). "Biopsy of the tumor revealed well differentiated tubular adenocarcinoma and papillary adenocarcinoma with enteroblastic differentiation which was characterized by clear cytoplasm and regarded as one of the histological features in AFP-producing cancer." (PMID 30191347, 2018). "Tumor markers evaluation revealed elevated level of AFP in all girls (186,1680 and 6434 ng/ml)." (PMID 30165903, 2018). "In support of our observations, a previous study has shown that ISG20 overexpression in HCC tumours was correlated with clinical parameters, such as vascular invasion, AFP levels and tumour sizes, as well as with poorer recurrence-free survival in HCC patients." (PMID 29963243, 2018). "Additionally, our patient’s serum tumor markers, including AFP and PIVKA-2, were within normal limits." (PMID 29916092, 2018). "In onestudy, exposure of HCC cells to sorafenib led to changes in UPR that affectedAFP production independent of an effect on cell viability, a finding thatsuggests that AFP could potentially serve as a biomarker of tumor proteostaticresponse." (PMID 29376136, 2018). "According to the results, inhibiting AFP expression significantly decreased tumour weight." (PMID 30301886, 2018). "EVs derived from AFP-expressing DCs are able to trigger potent antigen-specific anti-tumor immune responses and reshape the tumor microenvironment from an immunoinhibitory to an immunostimulatory setting in diverse HCC mice models including ectopic, orthotopic and carcinogen-induced HCC." (PMID 30369925, 2018). "Interestingly, there was a clear difference in the proportion of factors related to tumor aggressiveness and metastasis, such as high serum AFP levels, vascular invasion (p = 0.0002 for serum AFP levels and p = 0.0013 for vascular invasion)." (PMID 30274313, 2018). "Finally, we examined the possibility to predict the expression pattern of HPC markers in HCC as a factor related to tumour malignancy based on serum AFP and AFP-L3 levels using a Venn diagram." (PMID 29774107, 2018). "Hematological tumor marker tests revealed a significant increase in AFP (alpha-fetoprotein) values." (PMID 30314476, 2018).
tumor (continued). "The presence or absence of macroscopic PVT may therefore represent different HCC aggressiveness phenotypes, as judged by a significant increase in tumor multifocality and AFP levels in the PVT positive patients." (PMID 30009156, 2018). "Strong correlation between IGF2 and AFP levels and tumor diameter was found." (PMID 29702590, 2018). "The tumour markers were AFP 0.69UI, HCG 0.44UI and LDH 1240UI." (PMID 30792805, 2018). "The tumor markers AFP and L3 fraction were elevated to 102 ng/ml and 85.4%, respectively." (PMID 30203247, 2018). "AFP tumour marker is elevated in only 50–60% of cases of HCC." (PMID 30305894, 2018). "In addition, AFP (P=0.024), tumor number (P=0.027), tumor size (P<0.001), microvascular invasion (P=0.007), HBV-PIS (P=0.042), and HBV-ALBI (P=0.006) were independent prognostic factors of RFS." (PMID 30327670, 2018). "The results showed that LINC01138 was apparently overexpressed which occurred in 53.3% of the HCC samples, and its expression was positively correlated with tumour size, alpha-fetoprotein (AFP) level, and hepatitis B surface antigen (HBsAg) level, respectively." (PMID 29679004, 2018). "Additionally, lower CYP2A6 and CYP2C8 are associated with advanced clinicopathological features including tumor staging, vascular invasion, intrahepatic metastasis, and high alpha fetoprotein (all P < 0.05)." (PMID 30148168, 2018). "Tumor derived AFP could significantly inhibit the differentiation of DCs, and the DC cells restricted by tAFP still maintained the immature mononuclear cell-like morphology." (PMID 29805966, 2018). "Furthermore, the combined OR suggests that LDH was significantly correlated with gender, Child-Pugh grade, alpha-fetoprotein, vascular invasion, and tumor size." (PMID 30687735, 2018). "Tumour markers were AFP 4.5UI/l, HCG 8.02UI/L and LDH 3637UI/L." (PMID 30792805, 2018). "Interestingly, subgroup analyses showed that patients who received combined TACE and H101 therapy had significantly decreased cancer-specific mortality in the elevated-AFP and enlarged tumor subgroups." (PMID 29435900, 2018). "The tumour markers were AFP 0.9UI/L, HCG 19609UI/L and LDH 561UI/L." (PMID 30792805, 2018). "In addition to these two parameters, we included vascular invasion, histologic differentiation, the serum level of AFP, and tumor-downstaging to Milan criteria in our nomogram." (PMID 29416782, 2018). "Lamin B1 and AFP could both differentiate HCC patients with one tumor nodule (T1) from those with two or more tumor nodules (T2&Tm), as well as between those with tumor sizes >3 cm and ≤3 cm." (PMID 30467522, 2018). "Prognostic factors that have been previously identified in patients with HCC treated with TACE or TAI include hepatic functional reserve; tumor-specific factors, such as number, diameter, vascular invasion, and distribution in the liver; and serum AFP concentrations." (PMID 30041616, 2018). "At the same time, AFP level decreased rapidly with the step of tumor shrinking." (PMID 30334945, 2018). "Clinically, we found that USP4 is overexpressed in human HCC tissues compared with adjacent non-tumoral tissues and is significantly correlated with malignant phenotype characteristics, including tumor size, tumor number, differentiation, serum alpha-fetoprotein level, and vascular invasion." (PMID 29396555, 2018). "Furthermore, the univariate analyses showed that SDHB low expression, alpha-fetoprotein (AFP), tumor capsule, tumor size, tumor grades and pathological stages were associated with both disease-free and overall survival." (PMID 29449614, 2018). "The three miRNAs mir-21, mir-122, mir-192, together with AFP, are biomarkers that may be applied to improve diagnostics of HCC in HBV patients, especially in HBV-related LC patients with normal AFP levels or HCC patients with small tumor sizes." (PMID 29672637, 2018).
tumor (continued). "Demographic characteristics (including age, ethnicity, marital status), year of diagnosis, and clinical features (like TNM stage, SEER stage, pathological grade, AFP level, tumor size, therapy) were regarded as prognostic factors for HCC survival outcomes, which was similar with previous studies." (PMID 30445928, 2018). "However, when we combined all 3 parameters of MTD >5cm plus tumor multifocality plus AFP >100 IU/ml, an OR of 17.9 was obtained." (PMID 30009156, 2018). "AFP may also be directlyinvolved in tumor pathogenesis through its involvement in several mitogen andanti-apoptotic pathways, as well as potentially by exerting paracrine effects onimmune and other non-tumor cells." (PMID 29376136, 2018). "Age (P=0.001), neutrophil (P<0.001), monocyte (P<0.001), NLR (P<0.001), LMR (P<0.001), dNLR (P<0.001), total bilirubin (TB) (P=0.003), log (α-fetoprotein [AFP]) (P=0.004), tumor size (P<0.001), and log (tumor volume) (P=0.005) were significantly associated with MVI." (PMID 30254101, 2018). "The fibrolamellar variant of HCC (FHCC) is due to a heterozygous deletion on chromosome 19 that encodes a functional chimeric protein (DNAJB1-PRKACA) and characterized by being less aggressive with a normal alpha-fetoprotein (AFP) tumour marker and a female predominance." (PMID 30305894, 2018). "The tumor was therefore diagnosed as AFP-producing adenocarcinoma." (PMID 30191347, 2018). "BRG1 nuclear staining was observed in 57 of 77 (74.0%) tumour liver tissue from patients whose level of AFP was greater than 20 ng/ml, 19 of 36 (52.8%) tumour liver tissue from patients whose level of AFP was less than or equal to 20 ng/ml in cohort 2 (P < 0.05)." (PMID 29352111, 2018). "Multivariate analysis revealed that SML (HR, 1.675; 95% CI, 1.031–2.721; P = 0.037), serum AFP ≥ 20 ng/mL (HR, 2.550; 95% CI, 1.440–4.515; P = 0.001), and maximum tumor diameter ≥ 30 mm (HR, 1.925; 95% CI, 1.166–3.179; P = 0.010) were independently predictive of poor OS." (PMID 30041616, 2018). "Two nomograms, comprising WWOX, alpha‐fetoprotein (AFP), tumor size, and γ‐glutamyltransferase (γ‐GT), were constructed to obtain superior discriminatory abilities than conventional staging systems in terms of C‐index and clinical net benefit on decision curve analysis (DCA) for OS and RFS." (PMID 29905011, 2018). "Thus, on the whole, patients with PVT had larger and more multifocal tumors with higher AFP values, yet similar bilirubin levels, across the tumor size groups." (PMID 30009156, 2018). "Immunohistochemically, the tumor cells were positive for AFP, GPC3, and SALL4." (PMID 30228922, 2018). "In contrast, AFP levels were increased when the tumor size was smaller than 10 cm." (PMID 29672637, 2018). "High level of AFP is correlated with tumor size, vascular invasion and poorly differentiated HCC." (PMID 30355653, 2018). "Moreover, we constructed two novel nomograms comprising HBV-PIS, HBV-ALBI, AFP, tumor number, tumor size, and microvascular invasion, which allowed accurate prognostic prediction for OS and RFS of a patient with HCC after curative resection." (PMID 30327670, 2018). "Thus, AFP-expressing DC-derived EVs stimulate antigen-specific anti-tumor immune responses in vivo, eliciting suppression of tumor growth and prolonging mice survival." (PMID 30369925, 2018). "Similarly, significant factors of OS included Fib (P < 0.001), AFP (P < 0.001), size of largest tumor (P < 0.001), tumor number (P < 0.001), macro-vascular invasion (P < 0.001), micro-vascular invasion (P < 0.001), NLR (P = 0.041)." (PMID 27935864, 2017). "In our study, we found that the correlation between a higher level of AFP (AFP ≥ 20 ng), lower pathology grade (poor) and tumour recurrence and a lower expression level of INTS6 may be associated with poor prognosis in HCC patients." (PMID 28899352, 2017).
tumor (continued). "Univariate analysis identified the following prognostic factors predicting poor overall survival: NLR more than 4, AFP more than 400 ng/ml, multiple tumor targets, tumor diameter more than 5 cm, BCLC stage B, poor histological grading, and presence of microvascular invasion." (PMID 28155861, 2017). "A total of 16 features were analyzed, including tumor size, AFP level, and vascular invasion." (PMID 28487498, 2017). "Furthermore, sensitivity of AFP decreases from 52% to 25% when tumor diameter is >3 cm and <3 cm, respectively." (PMID 28077782, 2017). "It provided a perfect matching for tumor size and serum AFP strata." (PMID 27793027, 2017). "However, multivariable analysis revealed that only number of tumors (p = 0.001), size of the largest tumor (p = 0.009), and pre-transplant alpha-fetoprotein concentration (p = 0.049) were independent predictors of microvascular invasion." (PMID 28057916, 2017). "Factors with a p<0.10 were selected for inclusion in a multivariate analysis, which showed that age >66 years, Child-Pugh B/C, MELD >11, ECOG-PS >0, AFP level >100 ng/mL, tumor size >50 mm, vascular invasion, and extrahepatic spread remained significant factors of OS." (PMID 28954003, 2017). "BARD1 mRNA expression level in HCC tissues was significantly associated with TNM stage (P < 0.001), BCLC stage (P = 0.006), hepatitis B surface antigen (HBsAg) status (P = 0.005), size of tumor (P = 0.004), serum AFP levels (P = 0.008), and serum aspartate aminotransferase (AST) levels (P = 0.003)." (PMID 28794477, 2017). "Moreover, in tumor-derived AFP exposed DC there was a reduction in mitochondrial mass, number of active mitochondria, oxidative phosphorylation, and in the master regulator of mitochondrial biosynthesis, PGC1alpha." (PMID 28716068, 2017). "In addition, differentiation status (log-rank test: P=0.005), AFP (log-rank test: P=0.010), tumor size (log-rank test: P=0.001), and TNM stage (log-rank test: P=0.000) were all identified to be prognostic factors for OS of patients with HCC." (PMID 28546230, 2017). "However, the sensitivity of AFP is subject to the size and stage of tumor, which makes combined detection of multiple biomarkers relatively superior and more convincing." (PMID 28316892, 2017). "Moreover, the mean levels of the tumour markers AFP and PIVKA-II were 630 ng/mL and 2,098 mAU/mL, respectively, in the HCC group, which were significantly higher than those in the non-HCC group (11 ng/mL and 23 mAU/mL, respectively)." (PMID 28928439, 2017). "Multivariate Cox regression analysis for the entire cohort showed that alpha-fetoprotein level, alkaline phosphatase level, tumor size, metastasis, vascular invasion, and TACE with or without H101 were independent factors for OS, all of which were included in the nomogram." (PMID 28728568, 2017). "Hypoxia and tumor necrosis after therapy has been shown to lead to AFP decrease after treatment." (PMID 29156744, 2017). "However, it is challenging to monitor tumor recurrence and metastasis in 30–40% of low AFP levels patients with HCC." (PMID 28769812, 2017). "Serum AFP is the most widely used tumor marker in detecting patients with HCC." (PMID 28584302, 2017). "Serum AFP levels were monitored before every cycle to evaluate tumor response." (PMID 28969004, 2017). "Furthermore, EpCAM+ CTCs ≥ 2 were strongly associated with a shorter time of recurrence, greater vascular invasion, poor tumor differentiation and higher levels of alpha fetoprotein (AFP), an important HCC marker." (PMID 27738343, 2017). "Bivariable analysis confirmed the independent impact of pretransplant alpha-fetoprotein (p < 0.001; HR 2.88, 95% CI 1.66–5.00) and total tumor volume (p = 0.002; HR 2.35, 95% CI 1.35–4.07) on disease-free survival following their transformation to categorical variables." (PMID 28695391, 2017).
tumor (continued). "The variables tested by univariate analysis were sex, age, tumor size, α-fetoprotein (AFP), total bilirubin (TB), albumin (A), alanine aminotransferase (ALT), aspertate aminotransferase (AST), γ-glutamyl transferase (GGT), prothrombin time (PT), and HBVDNA status." (PMID 28700480, 2017). "Transcriptional upregulation of CYP2J2 and downregulation of sEH in HCC might explain the EET secretion and accumulation, related to the differentiation of tumor, tumor size and increased level of alpha-fetoprotein as well as intracellular Hcy level." (PMID 28030819, 2017). "Elevated AFP levels is the hallmark of this tumour and rapid decline in serum levels of AFP indicate absence of residual tumour after surgery." (PMID 28796980, 2017). "Interestingly, concerning the correlation between preoperative Fib and clinical characteristics, we found that an elevated Fib was positively related to Child-pugh stage, AFP, size of largest tumor, macro- and micro-vascular invasion." (PMID 27935864, 2017). "However, DJ-1 expression was not significantly although negatively correlated with OS in subgroups of AFP>200ng/ml or tumor size<5cm." (PMID 28036277, 2017). "Previous studies reported the serum albumin level, serum alpha fetoprotein level, recurrent tumor size, time interval from primary hepatectomy to first recurrence, and time interval from treatment of recurrent HCC to second recurrence were significant prognostic factors to overall survival." (PMID 29262662, 2017). "Nevertheless, high-risk cirrhotic HCC patients with high alpha-fetoprotein and concomitant excessive tumor burden are unlikely candidates for effective nontransplant therapies, particularly liver resection, which potentially increases transplant benefit." (PMID 28695391, 2017). "A Chi-square analysis showed that patients with higher GTSE1 expression were more likely to have multiple tumours and to have higher alpha-fetoprotein (AFP) levels, whereas patients with lower GTSE1 expression were prone to having a single tumour and lower AFP levels." (PMID 28698581, 2017). "This reduction in AFP levels correlated with tumor shrinkage." (PMID 27419635, 2017). "At study visits the tumor marker alpha-feto-protein (AFP) was measured during the treatment phase." (PMID 29098441, 2017). "However, the serum AFP level in patients with poorly differentiated tumor was significantly higher than that in patients with well-differentiated tumor (median 97.03 ng/ml vs. 36.38 ng/ml, P=0.0268)." (PMID 28423604, 2017). "Additionally, a recent report showed that a maximum value of AFP at a cut-off of 1000 ng/mL improved the performance of MC in predicting the tumor recurrence." (PMID 28276470, 2017). "However, NLR (P = 0.045), AFP (P = 0.000), tumor size (P = 0.004), alanine aminotransferase (ALT; P = 0.045), and APRI (P = 0.026) were significantly higher in patients with HCC having MVI." (PMID 29108352, 2017). "In addition, CENP-K mRNA expression level was positively correlated with the level of alpha-fetoprotein (AFP) (≥ 400 ng/ml) and tumor size (≥ 3 cm) (p < 0.05)." (PMID 29088763, 2017). "The mechanisms underlying the poor prognosis are not well understood although AFP has been reported to have a suppressive effect on lymphocyte transformation, to enhance tumor cell proliferation through the HGF and c-Met pathway, and to increase angiogenesis via VEGF expression." (PMID 28423604, 2017). "Metachronous liver metastasis may occur in approximately 50% of patients who undergo curative resection of the tumor within a year after surgery, and elevation of serum AFP level may be detected prior to appearance of symptoms and imaging detection." (PMID 28423604, 2017). "We found that the serum AFP level of patients with AFPGC was significantly associated with tumor differentiation, and that patient gender, tumor differentiation, Lauren classification, and number of metastatic lymph nodes showed significant association with the four subtypes of AFPGC." (PMID 28423604, 2017).